CKAP4 (cytoskeleton associated protein 4)
Diseases named in the same sentence as CKAP4 in open-access papers (continued):
Sharing a sentence is not in itself a finding about the gene and the disease.
glioma (7 papers, 2015 to 2023). A benign or malignant brain and spinal cord tumor that arises from glial cells (astrocytes, oligodendrocytes, ependymal cells). "CKAP4 is an essential regulator of carcinogenesis, and its upregulation promotes the malignant progression of human gliomas and is associated with poor patient survival." (PMID 37635346, 2023). "The results shown that CKAP4 is highly upregulated in glioma and high CKAP4 expressing tumors were associated with poor patient survival." (PMID 35935338, 2022). "Recently, the function of CKAP4 (Cytoskeleton-associated protein 4) on glioma was investigated in vitro and in an orthotopic brain tumor model in mice." (PMID 35935338, 2022). "Reversal experiments confirmed that CKAP4 overexpression inhibited the proliferation and migration effects of miR-671-3pin glioma cells." (PMID 33614703, 2020). "And targeting CKAP4 expression may be an effective therapeutic strategy for the treatment of human gliomas." (PMID 35935338, 2022). "And CKAP4 promotes malignant progression of gliomas via inhibiting Hippo signaling." (PMID 35935338, 2022). "Furthermore, a recent study revealed that exosomal microRNA-671-3p increases cell proliferation in glioma by directly targeting CKAP4; this affected the proliferation and significantly increased glioma cell migration, facilitating glioma growth." (PMID 34722277, 2021). "Additionally, in glioma, miR-671-3p has been shown to promote cell proliferation and migration in vitro and to decrease apoptosis through CKAP4 regulation." (PMID 33412518, 2021). "This study demonstrates that miR-671-3p is a predominant positive regulator of glioma progression, suggesting that the miR-671-3p/CKAP4 axis may serve as a possible therapeutic target or biomarker in glioma." (PMID 33412518, 2021). "Therefore, CKAP4, as a tumor suppressor, negatively regulated the progression of glioma." (PMID 33614703, 2020). "For example, CKAP4 inhibited EGFR activation in liver cancer and suppressed miR-671-3p induced cell proliferation and migration in glioma." (PMID 33614703, 2020). "In view of previous findings, the serum content of CKAP4 in ICC, renal cancer, glioma, bladder cancer, and other cancers should be evaluated and its diagnostic value should be assessed in further studies." (PMID 33614703, 2020). "In various tumors, CKAP4 could be used as an anticancer protein to inhibit tumor progression, such as HCC, ICC, and glioma." (PMID 33614703, 2020). "The expression of miR-671-3p, which promotes proliferation and migration in glioma cells, was high in glioma tissues and its target gene CKAP4 was of low expression in glioma tissues compared with the corresponding noncancerous tissues." (PMID 33614703, 2020).
COVID-19 (6 papers, 2021 to 2026). A disease caused by infection with severe acute respiratory syndrome coronavirus 2. "Additionally, this study examines and demonstrates the relationships between AD and COVID-19 with inflammatory signals such as interleukin 6 (IL-6), interleukin 1 (IL-1), and cytoskeleton-associated protein 4 (CKAP4)." (PMID 38259635, 2023). "It has been observed that interleukin (IL)-1, IL-6, cytoskeleton-associated protein 4 (CKAP4), and galectin-9 are all increased in both Alzheimer’s disease and COVID-19." (PMID 38078809, 2024). "Among inflammatory markers, interleukin 6 (IL-6), interleukin 1 (IL-1), cytoskeleton-associated protein 4 (CKAP4), and galectin-9 (GAL-9 or Gal-9) had received most attention as the common links between COVID-19 and AD manifestations." (PMID 33078369, 2021). "This extensive proteomic analysis unbiasedly identified IL6 and five novel proteins (CKAP4, Gal-9, IL-1ra, LILRB4 and PD-L1) to be associated with disease severity in COVID-19 cases." (PMID 33737684, 2021). "It is important to note that our putative biomarkers of disease progression in COVID-19 (IL6, CKAP4, Gal-9, IL-1ra, LILRB4 and PD-L1) were associated to NfL but to a much lesser extent to GFAP and tau." (PMID 33737684, 2021). "Plasma proteomics profiling also identified CKAP4 among the most perturbed proteins in COVID-19 patients and marked as an indicator of disease severity." (PMID 33078369, 2021). "In particular, we found an association between plasma proteins elevated in severe COVID-19, such as HGF, AREG, CKAP4, S100A12, NCF2, ITGB6, and a subpopulation of monocytes with lower expression of CD86 and HLA-DR, which are characteristics of myeloid-derived suppressor-like cells." (PMID 36829233, 2023). "COVID-19 and AD share common links with respect to angiotensin-converting enzyme 2 (ACE2) receptors and pro-inflammatory markers such as interleukin-1 (IL-1), IL-6, cytoskeleton-associated protein 4 (CKAP4), galectin-9 (GAL-9 or Gal-9), and APOE4 allele." (PMID 33078369, 2021). "Among these proteins, KRT19, TOP2B, AREG, HGF, CKAP4, ITGB6, and NCF2 had a higher expression (> twofold) in plasma samples of severe compared to moderate COVID-19 patients, whereas CLEC4C and LTA were among the few proteins that were expressed at lower levels in severe patients." (PMID 36829233, 2023).
pancreatic ductal adenocarcinoma (6 papers, 2020 to 2025). An infiltrating adenocarcinoma that arises from the epithelial cells of the pancreas. "Within TEXs, pancreatic ductal adenocarcinoma cells produce a type II transmembrane protein called cytoskeleton-associated protein 4 (CKAP4)." (PMID 35813829, 2022). "Pancreatic ductal adenocarcinoma (PDAC) cells have been reported to express and secrete CKAP4, with its function associated with tumorigenesis and induction of proliferation and metastasis through activation of the DKK1–CKAP4 axis." (PMID 41149482, 2025). "CKAP4 can be employed as a biomarker for pancreatic ductal adenocarcinoma diagnosis, staging, and targeted treatment, according to a study of patient blood samples." (PMID 35813829, 2022). "Then they confirmed that CKAP4 was released with exosomes from pancreatic ductal adenocarcinoma (PDAC) cells." (PMID 33614703, 2020). "A recent study has revealed that CKAP4 was released with exosomes from pancreatic ductal adenocarcinoma cells." (PMID 33614703, 2020). "In this context, a recent report demonstrated that cytoskeleton-associated protein 4 (CKAP4), a novel Dickkopf1 (DKK1) receptor, was selectively contained in sEVs from pancreatic ductal adenocarcinoma (PDAC) cells, not in sEVs from normal cells." (PMID 32847103, 2020). "Clinically, DKK1- and CKAP4-positive patients with pancreatic ductal adenocarcinoma have shorter 5-years survival and relapse-free survival than DKK1- or CKAP4-negative patients." (PMID 35355709, 2022).
bladder carcinoma (5 papers, 2010 to 2025). "This study investigated CKAP4 levels in bladder cancer specimens after radical cystectomy, and the association between CKAP4 levels, clinicopathological characteristics, and patient outcomes was analyzed." (PMID 40282454, 2025). "Background/Objectives: While cytoskeleton-associated protein 4 (CKAP4) has been associated with prognosis in various malignancies, its prognostic value for bladder cancer (BCa) remains unclear." (PMID 40282454, 2025). "In bladder cancer, CKAP4 promotes cancer cells mobility, migration, and tumor metastasis by organizing the cell surface stiffness in an increasing gradient from center to periphery." (PMID 41149482, 2025). "CKAP4-targeted aptamers successfully inhibit metastasis of bladder cancer cells in preclinical models." (PMID 41149482, 2025). "Cytoskeleton-associated protein 4 (CKAP4), which has been linked to worse outcomes in several types of cancer, has emerged as a novel biomarker to predict patient outcomes for bladder cancer following radical cystectomy." (PMID 40282454, 2025). "CKAP4 as a receptor of APF plays an important role in mediating bladder carcinoma cells proliferation." (PMID 33614703, 2020). "Another research showed that DKK3, the ligand of CKAP4, was highly expressed in bladder carcinoma cells." (PMID 33614703, 2020). "The current study shows that APF mediates its antiproliferative effects in T24 bladder carcinoma cells via the CKAP4 transmembrane receptor, as found previously for normal bladder epithelial cells." (PMID 21143984, 2010). "It seems that CKAP4 may have an emerging role in various malignancies such as bladder cancer, and cervical carcinoma, colorectal cancer, lung, pancreatic, esophageal, hepatic, and renal tumors." (PMID 41149482, 2025). "Since DKK3 is highly expressed in bladder carcinoma cells and acts as a ligand for CKAP4, it might function as a prognostic biomarker in this setting." (PMID 36497305, 2022). "Thus, whether CKAP4 and DKK3 associate with bladder carcinoma prognosis need further studies." (PMID 33614703, 2020). "In addition, the relationship between the expression of CKAP4 and its ligand DKK3 in bladder cancer tissues and the prognosis is unclear." (PMID 33614703, 2020). "Following CKAP4 knockdown, the inhibition effect of APF on T24 cell proliferation was eliminated, indicating the important role of the receptor in mediating the antiproliferation activity of APF in bladder cancer cells." (PMID 33614703, 2020). "However, neither the role of CKAP4 in regulation of bladder carcinoma cell proliferation, nor its role in mediating APF activity in bladder carcinoma cells, has yet been studied." (PMID 21143984, 2010).
cholangiocarcinoma (4 papers, 2022 to 2025). A carcinoma that arises from the intrahepatic biliary tree (intrahepatic cholangiocarcinoma) or from the junction, or adjacent to the junction, of the right and left hepatic ducts (hilar cholangiocarcinoma). "Furthermore, the DKK1/CKAP4 pathway upregulates the expression of plasmalemma vesicle-associated proteins in cholangiocarcinoma cells, which is positively linked to angiogenesis in various tumors." (PMID 40394415, 2025). "Surprisingly, DKK1 functions through the DKK1/CKAP4/PI3K pathway to augment the expression of plasmalemma vesicle-associated protein in cholangiocarcinoma cells, which is positively linked to angiogenesis in various tumors, hence also making this pathway a prospective anti-angiogenic target." (PMID 35355709, 2022). "As reported, Plvap can promote angiogenesis in cholangiocarcinoma through the DKK1/CKAP4/PI3K pathway, and maintain the ultrastructure and function of chorionic capillaries in retinal ECs." (PMID 39010027, 2024). "In cholangiocarcinoma, PLVAP is upregulated through a DKK1/CKAP4/PI3K‐Akt axis, correlates with micro‐vessel density and poor prognosis." (PMID 41431249, 2025).
interstitial cystitis (4 papers, 2012 to 2025). A rare chronic debilitating urogenital disease characterized by urinary frequency, urgency, and pelvic pain. "The normal function of CKAP4 has been associated with various non-cancerous conditions, including drug-induced cytotoxicity, interstitial cystitis/painful bladder syndrome, as well as atherosclerosis and structural heart diseases." (PMID 41149482, 2025). "Cytoskeleton-associated protein 4 (CKAP4) is a reversibly palmitoylated and phosphorylated transmembrane protein that functions as a high-affinity receptor for antiproliferative factor (APF)—a sialoglycopeptide secreted from bladder epithelial cells of patients with interstitial cystitis (IC)." (PMID 22536245, 2012). "Except for cancer diseases, CKAP4 has been related to noncancers, such as drug-induced cytotoxicity and interstitial cystitis/painful bladder syndrome (IC/PBS)." (PMID 33614703, 2020). "CKAP4, which binds to its ligand APF, could promote excessive proliferation of bladder epithelial cells and induce interstitial cystitis/painful bladder syndrome (IC/PBS)." (PMID 33614703, 2020). "Nonetheless, despite the fact that CKAP4 is involved in several inflammatory conditions such as interstitial cystitis, acute kidney injury, and chronic kidney disease, no such correlation has been proved yet for precancerous lesions like atrophic gastritis or intestinal metaplasia." (PMID 41149482, 2025). "The extracellular domain (AA 127–524) of CKAP4 is required for antiproliferative factor (APF) binding, which suggests that targeting this special region of CKAP4 to inhibit APF binding may be an effective strategy for the treatment of interstitial cystitis related to bladder pathology." (PMID 33614703, 2020).
atherosclerosis (3 papers, 2021 to 2024). A disease characterized by the build-up of fatty material and calcium deposition in the arterial wall resulting in partial or complete occlusion of the arterial lumen. "It has been revealed that CKAP4 exerts an suppressive effect on the α5β1 integrin recycling, while the the α5β1 integrin is closely associated with atherosclerosis and plays a key role in this disease." (PMID 34688276, 2021). "Therefore, we speculate that CKAP4 may participate in atherosclerosis by regulating the the α5β1 integrin, however, deeper investigation is needed to elucidate the underlying relationships." (PMID 34688276, 2021).
chronic kidney disease (3 papers, 2025). Impairment of the renal function secondary to chronic kidney damage persisting for three or more months. "Since CKAP4 gene expression is downregulated in glomeruli from patients with DKD but not in other chronic kidney diseases, we hypothesized a role for CKAP4 in the mechanisms leading to foot process effacement (FPE) in DKD." (PMID 40493405, 2025). "We identified the hub genes of CKD (Fn, Timp1, C3, Apoe, Trf, Fbn1, FGG, Penk, Ckap4, and Gpc3) through multiple bioinformatics analyses and successfully verified their expression in a mouse chronic kidney disease model." (PMID 40564035, 2025).
gastric cancer (3 papers, 2024 to 2025). A primary or metastatic malignant neoplasm involving the stomach. "Serum CKAP4 levels are associated with the pathological stage and histological grade of gastric cancer." (PMID 41149482, 2025). "CKAP4 is also increased in the serum of gastric cancer patients and it is reduced after surgery for gastric cancer." (PMID 41149482, 2025). "High levels of CKAP4 in gastric cancer tissues and gastric cancer cell cultures correlated to worse overall survival and tumor growth, respectively." (PMID 41149482, 2025). "The DKK–CKAP4 axis seems crucial for CKAP4′s oncogenic role in ESCC, gastric cancer, and CRC." (PMID 41149482, 2025). "Serum CKAP4 has been proven to be elevated in patients with PDAC, ESCC, gastric cancer, and CRC." (PMID 41149482, 2025).
Sepsis (3 papers, 2023 to 2025). Sepsis is defined as life-threatening organ dysfunction caused by a dysregulated host response to infection. "CKAP4 (cytoskeleton-associated protein 4) has garnered increasing attention for its role in lipid metabolism, sepsis, and AF." (PMID 41359645, 2025). "Group B Strep sepsis was significantly associated with multiple cell clusters, including C8_DC, C9_STOM, C10_ULK1, C12_mix, C13_UBE2Z, and C16_B, and its signature genes, including CKAP4, CPEB4, TSPO, and TXN, were significantly upregulated in multiple relevant clusters." (PMID 37919720, 2023). "Given its interaction with NF-κB, a key regulator of inflammation, the upregulation of CKAP4 in sepsis patients could provide a novel link between inflammatory signaling pathways and the progression of sepsis." (PMID 40665987, 2025). "Furthermore, CKAP4 expression is closely related to inflammatory responses, making it an important player in the pathophysiology of sepsis." (PMID 41359645, 2025). "We hypothesize that the variations in gene expression in sepsis patients occur in specific cells in the blood and then reflect a pattern of upregulation of genes CKAP4 and FCAR in whole blood samples along with downregulation of RNF4." (PMID 40665987, 2025). "Further analysis of the correlation between sepsis feature genes and immune cells revealed that CLU, GLPX, and CKAP4 were negatively correlated with CD4 naive T cells, while DPEP2 and BCL11B were positively correlated." (PMID 41359645, 2025). "In the case of these samples, a pattern consisting of upregulation of CKAP4 and FCAR along with downregulation of RNF4 decisively discriminates between sepsis patients and healthy samples." (PMID 40665987, 2025). "Overall, we report that a change in CKAP4, FCAR, and RNF4 expression patterns is a key feature of sepsis on the genomic level." (PMID 40665987, 2025). "Ultimately, by taking the intersection of the results from the three machine learning methods, we identified six feature genes in sepsis: CD81, CLU, GLRX, CKAP4, DPEP2, and BCL11B; and seven feature genes in atrial fibrillation: LDHB, CD81, PFKFB2, CKAP4, CXCR4, DPEP2, and RORA." (PMID 41359645, 2025). "Our analysis highlights CKAP4, FCAR, and RNF4 as key genetic drivers in sepsis-related variations." (PMID 40665987, 2025). "Under high λ conditions, we observed that the genes GLPX, CKAP4, CXCR4, and CLU maintained significant positive values, suggesting that these four genes may be key predictors of sepsis." (PMID 41359645, 2025). "Conversely, lower expression of CKAP4 and PLEKHO1 also associates with increased sepsis severity, suggesting a complex, possibly non-linear interaction in their regulatory role." (PMID 40665987, 2025). "Among all sepsis patients, the expression patterns of CKAP4 and PLEKHO1 do not show significant linearity, further supporting the idea that certain genes contribute uniquely to disease progression depending on their interaction networks and expression thresholds." (PMID 40665987, 2025). "Furthermore, this alignment emphasizes the potential for certain genes, like NONO and CKAP4, to serve as robust markers across the full spectrum of sepsis severity." (PMID 40665987, 2025). "Genes co-expressed with CKAP4 in C12_mix, involved in “PID pathway,” “Regulation of peptidase activity,” and “Vitamin D receptor pathway,” and might contribute to regulation of Group B Strep sepsis." (PMID 37919720, 2023). "Using our new plasma data (11 septic shock samples and 21 sepsis samples), the combinations of five genes (NONO, CKAP4, FCAR, PLEKHO1, BMP6) reached an overall accuracy of 93.75%, with a sensitivity of 81.82% and a specificity of 100.00%." (PMID 40665987, 2025). "While literature links NONO, FCAR, BMP6, RNF4, and RNASE2 to sepsis or Systemic Inflammatory Response Syndrome (SIRS), their interactions and the roles of PLEKHO1, OGFOD3, and CKAP4 in sepsis are less documented." (PMID 40665987, 2025).
Sepsis (continued). "We observe a clear relationship between gene expression and sepsis severity based on the plasma analysis from GSE49757 and the coefficient signs for the genes NONO, CKAP4, PLEKHO1, and BMP6." (PMID 40665987, 2025).
clear cell renal cell carcinoma (2 papers, 2020 to 2021). "CKAP4 overexpression promoted cell proliferation, invasion, and migration of clear cell renal cell carcinoma (ccRCC) cells." (PMID 33614703, 2020).